ODAM (odontogenic, ameloblast associated)
Description:
Tooth-associated epithelia protein that probably plays a role in odontogenesis, the complex process that results in the initiation and generation of the tooth. May be incorporated in the enamel matrix at the end of mineralization process. Involved in the induction of RHOA activity via interaction with ARHGEF and expression of downstream factors such as ROCK. Plays a role in attachment of the junctional epithelium to the tooth surface.
Synonyms: APIN; FLJ20513
Tractability: Antibody: its Gene Ontology location is reachable by antibodies, with high confidence; UniProt places it where antibodies can reach, with medium confidence; UniProt predicts a signal peptide or a membrane-spanning region.
Gene: Protein-coding gene on chromosome 4 (70,195,706 to 70,205,734, forward strand). Ensembl gene ENSG00000109205.
Subcellular location: Secreted; Cytoplasm; Nucleus
Subcellular location (Human Protein Atlas): Nucleoplasm; Cytosol
Pathways (Reactome):
Metabolism of proteins: Amyloid fiber formation
Gene Ontology:
Molecular function: protein binding
Biological process: inflammatory response; odontogenesis of dentin-containing tooth; positive regulation of epithelial cell proliferation involved in wound healing; positive regulation of gene expression; positive regulation of GTPase activity; positive regulation of protein phosphorylation; regulation of actin cytoskeleton organization; response to wounding
Cellular component: cell periphery; cytoplasm; cytosol; extracellular region; nucleoplasm; nucleus; supramolecular fiber
Genetic constraint (gnomAD): Loss-of-function variants: 22 observed, 22.53 expected, observed/expected ratio (o/e) 0.98, 90% interval 0.7 to 1.39. The upper end of that interval is the gene's LOEUF score, 1.39, which puts it in group 5 of 6, group 1 being the genes least tolerant of losing a copy. Missense variants: 206 observed, 198.51 expected, observed/expected ratio (o/e) 1.04, 90% interval 0.93 to 1.16. Synonymous variants: 86 observed, 68.48 expected, observed/expected ratio (o/e) 1.26, 90% interval 1.05 to 1.5.
Homologues: Orthologues: chimpanzee ODAM (97% identical), macaque ODAM (91% identical), rabbit ODAM (76% identical), dog ODAM (75% identical), pig ODAM (70% identical), mouse Odam (67% identical), rat Odam (66% identical), guinea pig ODAM (59% identical), tropical clawed frog odam (24% identical).